PGK1 (phosphoglycerate kinase 1)
Diseases named in the same sentence as PGK1 in open-access papers (continued):
Sharing a sentence is not in itself a finding about the gene and the disease.
breast carcinoma (continued). "Another protein from the neoplastic islands, PGK1, is a glycolytic enzyme that is involved in the tumor biology, angiogenesis, replication and repair of DNA and metastasis, and its increase has been investigated in breast cancer, pancreatic cancer, gastric cancer, and liver cancer." (PMID 30185791, 2018). "In breast cancer, hypoxia‐induced PGK1 lysine crotonylation (Kcr) coordinate glycolysis and TCA cycle, contributing to breast cancer progression." (PMID 40534132, 2025). "Elevated levels of NEAT1 in breast cancer enhance glycolysis by scaffolding key glycolytic enzymes, including PGK1, PGAM1, and ENO1, concurrently within the same cellular context, thereby promoting breast cancer progression and metabolism." (PMID 40711448, 2025). "Phosphoglycerate kinase 1 (PGK1) is upregulated in various human cancers, including PDAC, breast cancer, radioresistant astrocytoma, and multidrug-resistant ovarian cancer cells." (PMID 41213904, 2025). "In breast cancer, the transcription factor SIX1 induces the transcription of PGK1 by binding to its promoter region and recruiting the histone acetyltransferase HBO1, thereby promoting the Warburg effect and tumor growth both in vitro and in vivo." (PMID 39590319, 2024). "g., in breast cancer, FOXO3A-induced LINC00926 can inhibit tumor cell growth and metastasis by suppressing the PGK1-mediated Warburg effect." (PMID 39758420, 2024). "Therefore, PGK1 Kcr could be a promising candidate for diagnosing and treating breast cancer." (PMID 39513918, 2024). "PGK1 inhibition has been shown to reverse the Warburg effect and suppress EMT in both breast cancer and ovarian cancer." (PMID 39590296, 2024). "By lowering PGK1 expression, miR-16-1-3p can decrease glucose absorption and lactate generation in MDA-MB-231 breast cancer cells, reducing the Warburg effect." (PMID 37204526, 2023). "Several known proteins (including HSP90AB1, HSPB1, LDHA, ENO1, PGK1, KRT18, and AKR1C2) and pathways were observed between model breast cancer cell lines related to hormone response, cell metabolism, and cell morphology." (PMID 36937585, 2023). "PGK1 gene codifies for phosphoglycerate kinase 1 (PGK1), which is considered survival biomarker and invasion promoter in breast cancer." (PMID 36675137, 2023). "Many studies reported PGK1 as a prognostic gene in cancers, and it has been demonstrated to promote EMT and the progression of breast cancer." (PMID 36998462, 2023). "For the first time in this study, we used a comprehensive in silico approach and identified five proto-oncogenes (TUBA1B, SLC2A1, PGK1, CCND1, and NCAPD2) and two tumor suppressor genes (RPLP2, RPL37) as novel therapeutic targets against breast cancer." (PMID 35622738, 2022). "TUBA1B, SLC2A1, PGK1, CCND1, and NCAPD2 have been overexpressed in breast cancer tissues and their promoter region was hypomethylated (The graph on top shows gene expression and the graph at the bottom shows methylation beta value)." (PMID 35622738, 2022). "In this study, for the first time, we report five oncogenes (TUBA1B, SLC2A1, PGK1, CCND1, and NCAPD2) and two tumor suppressors’ genes (RPLP2, RPL37) as novel therapeutic targets in breast cancer." (PMID 35622738, 2022). "Notably, PGK1 could be used as an independent prognostic marker in breast cancer patients." (PMID 34291087, 2021). "We determined the expression of PGK1 and PGK2 in various human cancer types and found that it was significantly elevated in breast cancer vs. the normal tissue." (PMID 34291087, 2021). "PGK1 promotes the progression and metastasis of BRCA by adjusting the HIF-1α-mediated process of breast cancer epithelial-mesenchymal transition." (PMID 33584825, 2021). "A similar reduction was also observed after PGK1 depletion in 293T renal epithelial cells, MCF-7 and MDA-MB-231 breast cancer cells, HeLa cervical cancer cells, A2780 ovarian cancer cells, and A549 non-small cell lung cancer cells." (PMID 34403222, 2021).
breast carcinoma (continued). "Mechanistically, miR-16-1-3p inhibits PGK1 expression by directly targeting its 3′-UTR, and represses breast cancer cell growth and metastasis by inhibiting PGK1-mediated Warburg effect." (PMID 33344462, 2020). "While PGK1 is a well-characterized glycolytic enzyme with established links to tumor metabolism and hypoxia responses, MPHOSPH10 and MAP2K6 have received comparatively less attention in breast cancer." (PMID 40308601, 2025). "Previous research has indicated that PGK1, SDC1, SDC3, NUP43, and IL13RA1 may contribute to the development and progression of breast cancer." (PMID 39590319, 2024). "Further investigation into the role of PGK1 in breast cancer pathogenesis is anticipated to identify novel therapeutic targets and strategies." (PMID 39590319, 2024). "The PGK1 and HIF-1ɑ pathways stimulate the development and metastasis of breast cancer." (PMID 37723547, 2023). "As expected, we found that GSK3β or PGK1 depletion using their siRNAs significantly induced ALDH1A1 expression, suggesting that both GSK3β and PGK1 negatively modulated the stemness of breast cancer cells." (PMID 34403222, 2021). "Though there were no specific studies demonstrating the relationship between ALDOA/PFKL/PGK1 and TNBC, a previous study reported that aerobic glycolysis is crucial for modulating breast cancer cell proliferation, invasion, migration, and metastasis both in vitro and in vivo." (PMID 34490098, 2021). "Although the binding affinity of PGK1 and HTATSF1 needs to be further assessed in breast cancer." (PMID 34091600, 2021). "Furthermore, high expressions of PGK1 were significantly related with shorter OS, RFS, and DMFS in breast cancer patients." (PMID 34291087, 2021). "We found that tumors derived from breast cancer patients with metastases had higher PGK1 expression levels than those without metastases." (PMID 32276500, 2020). "Consistent with miR-16-1-3p inhibition of PGK1 in vitro and in mice, there was a negative correlation between miR-16-1-3p and PGK1 expression in breast cancer patients." (PMID 33344462, 2020). "These included genes such as SCUBE3, MARCKSL1 and PGK1 in lung cancer, SOX4 and GNAS in breast cancer and hepatocellular carcinoma, HEG1 in hepatocellular carcinoma, PLS3 in pancreatic adenocarcinoma, FBN1 and SPARC in gastric cancer and CST1 in gastric cancer and breast cancer." (PMID 40430098, 2025). "Additionally, PGK1 was not expressed in most breast cancers, some were weakly expressed, and few were moderately expressed." (PMID 36341328, 2022). "Furthermore, PGK1 might shape an inflamed tumor microenvironment following the evidence that PGK1 was positively correlated to the abundance levels of tumor-infiltrating immune cells such as CD8+ T cell and NK cell in breast cancer." (PMID 34790279, 2021). "Different methods and different samples had been used in the two studies and our study, while there are four genes (PGK1, GCN1L1, PRDX5, and SDHD) that were repeated and identified at least twice in three studies and might become valuable prognostic tools or therapeutic targets in breast cancer." (PMID 26576432, 2015).
gastric cancer (40 papers, 2006 to 2025). A primary or metastatic malignant neoplasm involving the stomach. "Upregulation of PGK1 is associated with the rapid progression and metastasis of stomach carcinoma, as well as with the progression of breast, prostate, pancreatic, and ovarian cancers." (PMID 30967137, 2019). "PGK1 inhibits susceptibility to chemotherapeutic drugs in gastric cancer cells and tumor stem cells." (PMID 28749413, 2017). "In this study, we demonstrated that TRIM8 regulates gastric cancer cell glycolysis by mediating PGK1 K63 ubiquitination." (PMID 41184227, 2025). "K63 ubiquitination stabilizes PGK1 and recruits ACAT1, driving PGK1 acetylation and promoting tumor angiogenesis in gastric cancer." (PMID 41184227, 2025). "We showed that TRIM8 and its induced K63 ubiquitination resulted in PGK1-dependent glycolysis and lactate accumulation in gastric cancer cells, which ultimately promoted tumor angiogenesis." (PMID 41184227, 2025). "MiR-1343-3p plays a tumor suppressive role in a variety of tumors, including gastric cancer, and the interaction between miR-1343-3p and PGK1 has also been reported, which is consistent with our research." (PMID 38459513, 2024). "This suggested that PGK1 played an important role in the promotion of gastric cancer cell migration by PTBP1." (PMID 38247832, 2024). "A previous study confirmed that GMRGs such as PKM2 (pyruvate kinase) and PGK1 (phosphoglycerate kinase 1) were up-regulated in gastric cancer cell lines." (PMID 37876534, 2023). "For instance, PGK1 acts in regulating angiogenesis, and its overexpression promotes gastric cancer cell invasiveness." (PMID 37767160, 2023). "Inhibition of PGK1 is able to increase the vulnerability of gastric cancer cells and overcome chemotherapeutic therapy resistance." (PMID 33747900, 2021). "PGK1 has been revealed to promote tumor proliferation and metastasis in various types of cancers, including astrocytoma, gastric cancer and colon cancer." (PMID 30925862, 2019). "In a further previous study, when profiling gene expression in diffuse primary gastric cancer, we observed a significant overexpression of PGK1, the chemokine CXCR4 and its ligand CXCL12 in PM patients." (PMID 31198853, 2019). "PGK1 was expressed not only in the cytosol, but also in the nucleus of malignant cells, both in the preclinical model and in human gastric cancer." (PMID 31198853, 2019). "Previous studies reported that PGK1 is significantly upregulated in various malignant tumors, such as gastric carcinoma, hepatocellular carcinoma and pancreatic ductal adenocarcinoma." (PMID 30953511, 2019). "Taken together, gankyrin can potentiate the mTORC1 signaling via a PGK1-AKT pathway in gastric cancer." (PMID 30420909, 2018). "A mouse model study of metastatic gastric cancer demonstrated that the overexpression of PGK1 significantly increased the invasive and metastatic behavior of the implanted gastric tumors." (PMID 29954422, 2018). "It has been also reported that PGK1 stimulates the metastasis in prostate cancer, and promotes the tumor invasion and metastasis in gastric cancer." (PMID 28903403, 2017). "Increased PGK1 in gastric cancer is considered as a biomarker of advanced gastric cancer and is followed by increasing intracellular ATP levels." (PMID 25652794, 2015). "In the studies on gastric cancer a direct relationship between PGK1 signalling and CXCR4 is observed and supports the importance of interaction between glucose metabolism and chemokine function." (PMID 24376734, 2013). "This activity facilitates PGK1-mediated glycolysis, lactate accumulation and triggers a significant increase in endothelial cell migration and tube formation, which ultimately accelerates tumor angiogenesis in gastric cancer." (PMID 41184227, 2025).
gastric cancer (continued). "In summary, our findings elucidate a novel mechanism underlying the upregulation of angiogenesis mediated by K63 ubiquitination-regulated glycolysis in tumor cells and provide a molecular basis for eliminating gastric cancer angiogenesis by targeting TRIM8-dependent PGK1 K63 ubiquitination." (PMID 41184227, 2025). "Similarly, this study reveals the mechanism by which the key glycolysis-limiting enzyme PGK1 promotes lapatinib resistance in HER2-positive gastric cancer." (PMID 40786054, 2025). "Regulating PGK1 protein levels or the glycolysis pathway may become a new strategy to improve the sensitivity of HER2-positive gastric cancer patients to lapatinib." (PMID 40786054, 2025). "This study indicates that regulating the expression levels of PGK1 impacts the sensitivity of HER2-positive gastric cancer to lapatinib, and potentially serving as a therapeutic strategy for HER2-positive gastric cancer patients who do not respond to lapatinib." (PMID 40786054, 2025). "Thus, the mechanism of the circGLIS3/miR-1343-3p/PGK1 axis in gastric cancer progression was determined." (PMID 38459513, 2024). "To determine whether PGK1 is the downstream target of circGLIS3, we knocked down circGLIS3 in a gastric cancer cell line and detected the expression level of PGK1 through western blotting." (PMID 38459513, 2024). "We performed rescue assays to verify whether PTBP1 promotes gastric cancer cell migration in a PGK1-dependent manner." (PMID 38247832, 2024). "For instance, PGK1 inhibition could counteract chemoresistance to intraperitoneal 5-fluorouracil in gastric cancer." (PMID 34790279, 2021). "Moreover, the mRNA level of gankyrin and PGK1 was found to be correlated in 414 gastric cancer samples according to the TCGA cancer genome database by Pearson's correlation analysis." (PMID 30420909, 2018). "PGK1 is a potential marker and a promoting enzyme for peritoneal dissemination in gastric cancer." (PMID 28749413, 2017). "PGK1 also appears to be a crucial enzyme for peritoneal dissemination of gastric cancer." (PMID 24376734, 2013). "Therefore, we further investigated whether PGK1 in gastric cancer also activates EMT and promotes metastasis of gastric cancer cells by regulating SNAIL expression." (PMID 38247832, 2024). "Moreover, PGK1 is also described to induce invasiveness in gastric cancer cells, and to explore whether our molecule could influence this activity, KATO III cells were incubated with 100 μM TatA for 24 h and a Transwell invasion assay was performed." (PMID 37767160, 2023). "Hence, PGK1 is a promoting enzyme for peritoneal dissemination in gastric cancer." (PMID 27526934, 2016). "PGK-1 may also induce the differentiation of gastric cancer stem cells." (PMID 24423398, 2013). "Phosphoglycerate kinase 1 (PGK1) plays a crucial role in ATP production through glycolysis and is significantly overexpressed in gastric cancer tissues." (PMID 40365984, 2025). "In gastric cancer KATO III cells, tatridin A reduces invasiveness by antagonizing PGK1, an oncoprotein that promotes proliferative and anti-apoptotic signaling cascades, along with the downregulation of chemokine receptor 4 (CXCR4) and β-catenin." (PMID 41149747, 2025). "PGK1 is K48 ubiquitinated and degraded by TRIM50, which inhibits glycolysis and the malignant progression of gastric cancer." (PMID 41184227, 2025). "We also detected changes in PGK1, PI3K, AKT, vimentin and related phosphorylation levels in gastric cancer cells after coculturing circGLIS3-knockdown exosomes and NC exosomes." (PMID 38459513, 2024). "For instance, the relationship between PGK1 and CXCR4/CXCL12/β-catenin has been established in gastric cancer and hepatocellular carcinoma." (PMID 38163864, 2024). "Since PGK1 is described to influence CXCR4 and β-catenin expression in gastric cancer cells, promoting peritoneal carcinomatosis, KATO III cells were incubated with 100 μM TatA for 24 h, and CXCR4 and β-catenin expression was evaluated by RT-qPCR." (PMID 37767160, 2023).
gastric cancer (continued). "PGK1 pS203 and PDHK1 pT338 were also independent predictors of short OS in liver, lung, and stomach cancer." (PMID 31578148, 2019). "Our findings highlight the pro-angiogenic role of TRIM8 in gastric cancer through K63 ubiquitination regulated-glycolysis and providing a potential strategy to eliminate gastric cancer angiogenesis by targeting TRIM8 -dependent PGK1 K63 ubiquitination." (PMID 41184227, 2025). "Consequently, we decided to investigate the correlation between PGK1 and the sensitivity of HER2-positive gastric cancer to lapatinib." (PMID 40786054, 2025). "Mechanically speaking, in glioma, LHX9 was found to negatively interact with phosphoglycerate kinase 1 (PGK1), which dominates in the aerobic glycolysis pathway; while in gastric cancer, it mainly activates pyruvate kinase M2 (PKM2) to promote tumor progression." (PMID 38902711, 2024). "Additionally, it has been reported that the heightened expression of PGK1, along with its signaling targets, CXCR4 and β-catenin, in gastric cancer cells promotes peritoneal carcinomatosis." (PMID 38136210, 2023). "Several studies have demonstrated PGK1 can enhance the proliferation and migration ability of tumors by activating CXCR4 in gastric cancer and neuroblastoma, but PGK1/CXCR4/ERK molecules and related signaling pathways have not been investigated in RCC in previous reports." (PMID 35121728, 2022). "In addition, the analysis of TCGA data revealed the up-regulation of PGK1 and G6PD in common cancers such as colon, lung and gastric cancers." (PMID 32028979, 2020). "This study demonstrates that the level of PGK1 protein is directly correlated with the sensitivity of HER2-dependent gastric cancer cells to lapatinib, providing a potential strategy for the application of lapatinib in patients with gastric cancer who have high HER2 expression." (PMID 40786054, 2025). "Notably, differences in PGK1 mRNA expression between gastric cancers disseminating or not disseminating to the peritoneum were comparable with values in our orthoptic xeno-transplanted in-vivo mouse model." (PMID 31198853, 2019). "PGK1 also appears to be a crucial enzyme for peritoneal dissemination of gastric cancer in both CXCR4/SDF1-dependent and by CXCR4/SDF1-independent mechanisms, making high levels of PGK1 essential for tumor growth and metastasis and showing a direct relationship between PGK1 signalling and CXCR4." (PMID 24376734, 2013). "In addition, we showed that K63 ubiquitination was required for PGK1-induced glycolysis and angiogenesis in gastric cancer cells expressing TRIM8, further supporting the essential role of TRIM8-mediated PGK1 K63 ubiquitination in the metabolism and angiogenesis of gastric cancer." (PMID 41184227, 2025). "However, the relationship between H19 and pgk1 in gastric cancer has not yet been reported." (PMID 37821504, 2023). "Therefore, PGK-1 was considered to be not suitable for the diagnosis of gastric cancer." (PMID 17187689, 2006). "This study indicates that regulating the expression level of PGK1 impacts the sensitivity of HER2-positive gastric cancer to lapatinib, potentially serving as a therapeutic strategy for HER2-positive gastric cancer patients who do not respond to lapatinib." (PMID 40786054, 2025).